AGO2 (argonaute RISC catalytic component 2)
Diseases named in the same sentence as AGO2 in open-access papers (continued):
Sharing a sentence is not in itself a finding about the gene and the disease.
melanoma (continued). "AGO2-ex1/3 is substantially expressed in different melanoma cell lines and patient-derived tissue samples." (PMID 35943635, 2022). "To date, alteration in the Ago2 gene expression (both up and down-regulation) has been identified across multiple cancer types, including colorectal, urothelial, prostate and melanoma." (PMID 31324173, 2019). "It was previously reported that Ago2 protein and mRNA levels were differentially regulated in melanoma." (PMID 31324173, 2019). "In our previous study, we showed that the observed reduction in AGO2 expression in melanoma resulted in decreased siRNA and miRNA functionality and phenotypic effects, such as a higher migratory potential of melanoma cells." (PMID 27518285, 2016). "We also identified decreased overall AGO expression in melanoma derived cell lines compared to other tumor cell lines and normal tissues, with the largest differences in AGO2 expression." (PMID 27518285, 2016). "Future studies should evaluate contribution of hyper-sumoylation to Ago2 protein reduction in melanoma and in other malignancies, which likely contributes to deregulation of miRNA expression in cancers." (PMID 25036361, 2014). "In line with our data, a recent report demonstrated that melanoma cells display strong reduction of Ago2 expression on the protein level, while the mRNA level is unchanged, implying post-translational control." (PMID 25036361, 2014). "Further, expression of AGO2-ex1/3 could also be detected in RNA originating from different melanoma tissue samples." (PMID 35943635, 2022). "This discovery represents an interesting insight into a so far unknown molecular mechanism regarding the miRNA pathway and makes AGO2-ex1/3 an interesting new target for possible future therapeutic approaches in melanoma." (PMID 35943635, 2022). "In our study, we observed a strong reduction of melanoma cell growth after knockdown of AGO2-ex1/3." (PMID 35943635, 2022). "Additionally, two mutant NRAS-driven melanoma cell lines (Mel-Juso; NRASQ61L/WT, and SK-MEL-2; NRASQ61H/Q61H) demonstrated marked growth reduction following loss of AGO2." (PMID 35923912, 2022). "MiR-25-3p is the most abundant miRNA in melanoma cells (29,562 mean normalized reads) in the list of miRNAs whose target genes are significantly enriched after AGO2-ex1/3 knockdown and which are also significantly upregulated in primary melanoma cells compared to NHEM." (PMID 35943635, 2022). "To analyze the functional relevance of AGO2-ex1/3 expression on melanoma cells, we first investigated in which way the altered AGO2-ex1/3 mRNA could be translated." (PMID 35943635, 2022). "Thus, we performed anti-AGO2 RIP in melanoma cells after transient transfection of miR-145-5p mimics." (PMID 33311650, 2021). "The down-regulation of AGO2 in melanoma cell lines is greater than that of the other AGOs." (PMID 27518285, 2016). "Different experimental approaches pointed to a potent translocation of AGO2 into the nucleus in SHSY5Y neuroblastoma, A375 melanoma cells, HEK293 kidney cells, and U2OS bone cancer cells upon silencing of LMNA expression." (PMID 38994560, 2024). "Ras (mutant HRAS and NRAS)-induced senescence involved ROS and EGFR-argonaute 2 (AGO2) signaling in various human cancer cells, including HeLa, melanoma cells, and bladder cancer cells." (PMID 36834846, 2023). "Especially AGO2, the most abundant AGO protein in human cells, is significantly downregulated in melanoma compared to healthy melanocytes." (PMID 35943635, 2022). "Therefore, AGO2-ex1/3 may play a considerable role for general miRNA function in melanoma cells." (PMID 35943635, 2022). "Among those, miR-105-5p is the miRNA whose target genes are most strongly enriched after AGO2-ex1/3 knockdown (NES − 2.04) and which is also significantly upregulated in melanoma cells." (PMID 35943635, 2022).
melanoma (continued). "Next, RIP assay exhibited that NCK1-AS1, miR-526b-5p and ADAM15 were all significantly enriched in Ago2 antibody groups, suggesting the interplay among miR-526b-5p, NCK1-AS1 and ADAM15 in melanoma cells." (PMID 34247598, 2021). "The melanoma cell lines displayed AGO distributions in percent of 40% to 50% AGO1, 26% to 49% AGO2, 7% to 20% AGO3 and 4% to 11% AGO4." (PMID 27518285, 2016). "Next, we determined the mRNA expression of AGO1, AGO2, AGO3 and AGO4 in different melanoma cell lines derived from primary tumors and metastases and in non-melanoma tumor cell lines." (PMID 27518285, 2016). "The AGO protein expression patterns relative to each other were similar for AGO2 and AGO4 (47–55% for AGO2; 7–10% for AGO4 of the total AGO protein pool) in the melanoma cell lines." (PMID 27518285, 2016). "To confirm the effect a knockdown of AGO2-ex1/3 has on melanoma cell growth and to rule out off-target effects, we designed a second siRNA targeting AGO2-ex1/3 which is shifted by a few nucleotides from the siAGO2-ex1/3." (PMID 35943635, 2022). "Considering that the precipitation was caused by the existence of RNA-induced silencing complexes (RISCs) comprising of Ago2 and microRNAs (miRNAs), it was hypothesized that NCK1-AS1 could bind to specific miRNAs in melanoma cells." (PMID 34247598, 2021). "Here, HepG2 and CaCo2 cells had the highest AGO2 protein expression (82% for HepG2; 85% for CaCo2), whereas the percentile distribution of AGO proteins in SW1353, MCF7 and HeLa cells was more similar to that in the melanoma cell lines." (PMID 27518285, 2016). "Repression of AGO2 protein has been found in human lung adenocarcinomas and in melanoma, for which the mRNA level of AGO2 did not change." (PMID 24904827, 2014). "The molecular mechanisms behind this AGO2 downregulation in melanoma are currently not understood." (PMID 35943635, 2022). "Additionally, DGCR8 and AGO2 mRNA expression levels analysis did not even show any significant differences between malignant melanomas (primary cutaneous malignant melanoma and cutaneous malignant melanoma metastases) and benign melanocytic nevi." (PMID 23775303, 2014). "The new finding in this study, that the total amount of AGO protein is markedly reduced in melanoma cell lines but not in other types of tumor cells, with the greatest reduction in AGO2, could serve as an explanation for the relatively up-regulated miRNA expression pattern." (PMID 27518285, 2016). "Next, we did immunoprecipitation experiments using an antibody against AGO2, an essential component of RISC, in keratinocytes, which express miR-944, and in WM-266-4 melanoma cells, which do not express miR-944, and subsequently performed RT-qPCR." (PMID 26202967, 2015).
cervical carcinoma (14 papers, 2017 to 2024). A carcinoma arising from either the exocervical squamous epithelium or the endocervical glandular epithelium. "DDX17 also controls the miRNA abundance by stabilizing AGO2 and posttranscriptionally regulating its expression in a proteasome-dependent manner in cervical cancer cells." (PMID 38689093, 2024). "In cervical cancer, miR-346 enhances Ago2 expression to regulate the activity of other miRNAs and migration and invasion." (PMID 35524319, 2022). "AGO2 related RIP assays revealed that circEPSTI1, MSH mRNA, and miR-370-3p were all enriched in the AGO2 protein in SiHa and HT-3 cervical cancer cell lines." (PMID 35779530, 2022). "A similar mechanism of GRSF1 interaction with AGO2 in a miR-346-dependant manner, leading to up-regulate the expression of AGO2, has been described for cervical cancer." (PMID 28522960, 2017). "In addition, GRSF1 participates in the miR-346-mediated promotion of the malignant phenotype of cervical cancer cells by enhancing AGO2." (PMID 34998399, 2022). "lncRNA799 and miR-454-3p were found to be enriched in Ago2-containing miRNA-containing ribonucleoprotein complexes in comparison with the controls (immunoglobulin G [IgG] immunoprecipitates); this indicates that the Ago2 protein directly binds to lncRNA799 and miR-454-3p in cervical cancer cells." (PMID 30439646, 2018). "In addition, up-regulation of AGO2 promoted the activity of some miRNAs and the malignant phenotype of cervical carcinoma." (PMID 28903378, 2017). "By way of this translation process independent of argonaute RISC catalytic component 2 (AGO2), miRNA-346 enhances proliferation in cervical cancer cells." (PMID 32825005, 2020). "Therefore, we performed CRISPR-Cas9 KO of Lamin A in A375 and SHSY5Y, two cancer cell lines negative for nuclear AGO2, and in HeLa cervical cancer cells, which are positive for nuclear AGO2." (PMID 38994560, 2024).
colorectal cancer (14 papers, 2012 to 2024). A primary or metastatic malignant neoplasm that affects the colon or rectum. "In humans, germline mutations in argonautes (AGO1 and AGO2) have been associated with defects in neurodevelopment, while somatic mutations in AGO2 appear to be common in gastric and colorectal cancers with high microsatellite instability." (PMID 38594249, 2024). "Moreover, the variations in genomic structure of AGO2, such as copy number change or frameshift mutation, were reported to be associated with several cancers including multiple myeloma, gastric and colorectal cancer." (PMID 22639842, 2012). "AGO2 overexpression has been reported in several carcinomas, including breast, head and neck squamous cell, nasopharyngeal, urothelial, ovarian and colorectal carcinomas." (PMID 36454786, 2022). "Then, we examined the expression levels of AGO2, E-cadherin, and vimentin in 284 colorectal cancer tissue samples." (PMID 33846300, 2021). "Ago2 and related enzymes involved in miRNA biogenesis are important effectors in colorectal carcinomas." (PMID 32244548, 2020). "Conversely, the impairment of Ago2/miR-185-3p axis may promote colorectal cancer metastasis in colorectal cancer tissues." (PMID 34991639, 2022). "In this study, we found that the protein expression of Argonaute 2 (AGO2), a key regulator of miRNA processing, was downregulated in colorectal cancer (CRC) tissues, which was also consistent with the findings of the Clinical Proteomic Tumor Analysis Consortium (CPTAC)." (PMID 33846300, 2021). "RNA pull-down assays also confirmed that SNHG1 could directly bind with AGO2 in colorectal cancer cells." (PMID 30266084, 2018). "Furthermore, in colorectal cancer cells, Ras-MEK signaling phosphorylates the RNA-binding protein Ago2, which reduces the exosome secretion of Ago2 and Ago2-bound miRNAs." (PMID 38203424, 2023). "In addition, RNA immunoprecipitation (RIP) assay results revealed that SNHG1 and miR-154-5p were significantly enriched in AGO2-containing micro-ribonucleoprotein complexes, suggesting that the AGO2 protein bound to SNHG1 and miR-154-5p directly in colorectal cancer cells." (PMID 30266084, 2018).
neuroblastoma (12 papers, 2014 to 2025). Neuroblastoma (NB) is the most common solid, extracranial childhood tumor. "Higher expression of HIF-2α, AGO2, or eIF4E was observed in NB specimens with advanced international neuroblastoma staging system (INSS) stages or MYCN amplification." (PMID 27276678, 2016). "We next transfected N2a neuroblastoma cells with myc-Ago2, the SUMO conjugating enzyme Ubc9, and conjugatable or non-conjugatable (lacking the C-terminal diglycine motif required for conjugation) YFP-tagged SUMO1 and SUMO2." (PMID 26188511, 2015). "Because the novel miRNA candidates had strong representation in human brain, we repeated the experiment in differentiated SH-SY5Y neuroblastoma cells, knocking down Dicer, Drosha, Argonaute 2 (Ago2) or DGCR8." (PMID 24708865, 2014). "To test this hypothesis, we knocked down three core enzymes of the miRNA pathway, a Microprocessor component Drosha, the pre-miRNA processing ribonuclease Dicer and the RISC endonuclease Ago2, in neuroblastoma cells." (PMID 29859124, 2018). "Due to the relevance of Ago2 protein complex composition, we aimed to find partners of the protein complexes containing human Ago2 (hAgo2) in SH-SY5Y neuroblastoma cells." (PMID 35326503, 2022). "Searching for Ago2 partners by immunoprecipitation and LC-MS/MS analysis, we isolated among other proteins the Serpine mRNA binding protein 1 (SERBP1) from SH-SY5Y neuroblastoma cells." (PMID 35326503, 2022). "We found that reduced Lamin A levels significantly induce nuclear influx of AGO2 in SHSY5Y neuroblastoma and A375 melanoma cancer cell lines, which normally have no nuclear AGO2." (PMID 38994560, 2024).
glioblastoma (11 papers, 2010 to 2024). The most malignant astrocytic tumor (WHO grade IV). "Argonaute 2 (Ago2) and GW proteins that act as direct partners of miRNAs are often susceptible to somatic mutations in glioblastoma, which are accompanied by a high level of instability of microsatellite tumor DNA." (PMID 34692698, 2021). "To investigate how AGO2-bound genes carrying L2 in their 3’UTR are affected in glioblastoma we conducted AGO2 RIP, followed by total RNA sequencing." (PMID 30865625, 2019). "We found that, as in cortex samples, AGO2-bound small RNAs in glioblastoma tissue displayed a high enrichment in reads of 20–24 nt while input samples had a broad RNA size profile." (PMID 30865625, 2019). "In two different studies on renal cell carcinoma and glioblastoma, it has been shown that miR-21 targeted and suppressed the expression of the tumor suppressor lncRNA CASC2 (cancer susceptibility candidate 2) in an AGO2-dependent manner." (PMID 29147648, 2017). "Further, MALAT-1, a nuclear lncRNA, was reported to be targeted by miR-9 in an Ago-2-dependent manner in the nuclei of Hodgkin’s lymphoma and glioblastoma cell lines." (PMID 28715488, 2017). "To examine whether the QKI isoforms associate with Ago2, a member of the RISC complex, we performed co-immunoprecipitations in the U343, a human glioblastoma cell line known to express the three major QKI isoforms (QKI-5, -6, and -7)." (PMID 20862255, 2010). "We first conducted AGO2 RIP, followed by small RNA sequencing, on human brain biopsies obtained from glioblastoma patients (n = 6)." (PMID 30865625, 2019). "EIF4G2 was previously identified as a direct target of miR-139 in AML, with luciferase assays identifying binding sites in both the 3′UTR and 5′UTR, while in glioblastoma, only the 3′UTR binding site was validated with reporter assays and also anti-Ago2-mediated RNA-immunoprecipitation assays." (PMID 33562636, 2021). "In contrast, we did not detect any AGO-bound L2b-carrying genes in glioblastoma tissue, although they were bound to AGO2 in cortex samples." (PMID 30865625, 2019). "Together with our finding that L2b-carrying transcripts are not bound to AGO2 in glioblastoma tissue, this suggests that miR-95 could play an important role in the regulation of transcripts related to tumor progression or tumor defense in glioblastoma." (PMID 30865625, 2019). "Thus, this analysis directly links the altered expression of L2b-derived miR-95 to the lack of L2b-carrying targets bound to AGO2 in glioblastoma tissue." (PMID 30865625, 2019). "In the present study, we show that the cytoplasmic QKI isoforms, QKI-6 and QKI-7, but not nuclear isoform (QKI-5), localize with Ago2, PABP1, and TIA1 within stress granules in the U343 glioblastoma cell line and in primary rat oligodendrocytes." (PMID 20862255, 2010). "Ago2 has been shown to interact with the QKI-6 RNA binding protein in stress conditions in cytoplasmic granules and in turn QKI-6 colocalizes with Mbp mRNA in stress granules of U343 human glioblastoma cells, but an involvement of the miRISC was not suggested." (PMID 26379499, 2015). "Moreover, it has been shown that pristimerin, a natural-occurring quinone methide triterpenoid with anticancer effects, inhibits glioblastoma progression by targeting two receptors, the protein tyrosine phosphatase, non-receptor type 1 (PTPN1), and Argonaute 2 (AGO2) via miR-542-5p." (PMID 38730608, 2024).
myeloma (11 papers, 2012 to 2022). "Global increases in miRNA expression are seen in cases with high-risk multiple myeloma (MMs) with increased expression of Ago2." (PMID 35459267, 2022). "Overexpression or enhanced activity of Ago2 elicited specific changes in miRNAs and mRNAs and showed a strong relationship with high-risk myeloma." (PMID 34483916, 2021). "Overexpression or enhanced activity of Ago2 elicited specific changes in miRNAs and mRNAs and had a strong relationship with high-risk myeloma." (PMID 34483916, 2021). "Previous studies identified an association between AGO1 and AGO2 and ovarian carcinoma, myeloma angiogenesis, as well as with an angiogenesis defect model related to inflammation." (PMID 31724726, 2019). "Previous work demonstrated that changes in Ago2 gene copy can affect expression levels and correlate with high-risk disease in multiple myeloma." (PMID 31324173, 2019). "Previous work found that increased Ago2 mRNA expression was associated with increased AGO2 gene copy number, and this was significantly associated with a poorer disease outcome in high-risk multiple myeloma." (PMID 31324173, 2019). "A previous study showed that elevation of the total miRNA expression levels in high-risk myeloma cells might be secondary to AGO2 dysregulation." (PMID 24886719, 2014). "Accumulations of MTA2 and AGO2 in the cytoplasm of myeloma cells were observed in the BM samples collected at NDMM and RRMM." (PMID 36454786, 2022). "In MM, dysregulated AGO2 expression contributes to MM pathogenesis, myeloma cell growth and survival, apoptosis, angiogenesis and drug resistance mechanisms." (PMID 36454786, 2022). "The results revealed significantly elevated VEGF protein expression in the supernatants from the AGO2-overexpressing myeloma cell lines and decreased expression in the AGO2-knockdown cell lines." (PMID 24886719, 2014). "To investigate the relationship between the AGO2 protein expression levels and angiogenesis in MM, we detected the AGO2 protein levels in bone marrow biopsies from MM patients using an anti-AGO2 antibody and found that AGO2 protein localized in the myeloma cell cytoplasm." (PMID 24886719, 2014). "Our study, however, revealed a novel role and mechanism of AGO2 as an enhancer of myeloma angiogenesis through miRNA dysregulation, including the upregulation of pro-angiogenic miRNAs such as the let-7 family members and the miR-17/92 cluster and downregulation of the anti-angiogenic miRNA miR-145." (PMID 24886719, 2014). "To validate the pro-angiogenic functional role of AGO2 in MM, we used lentiviral transfection of an AGO2-shRNA to silence AGO2 expression in the H929 and LP-1 myeloma cell lines (H929-si-AGO2 and LP-1-si-AGO2) and also generated scramble controls (H929-si-NC and LP-1-si-NC)." (PMID 24886719, 2014). "In contrast, supernatants from the AGO2-overexpressing U266 and OCI-My5 myeloma cell lines accelerated tube formation." (PMID 24886719, 2014). "We further established stable AGO2-overexpressing U266 and OCI-My5 myeloma cell lines (U266-pcDNA3-AGO2 and OCI-My5-pcDNA3-AGO2) and empty vector controls (U266-pcDNA3 and OCI-My5-pcDNA3)." (PMID 24886719, 2014).
asthma (9 papers, 2020 to 2025). "The presence of the argonaut (Ago2) gene among highly associated asthma genes in this study could support previous reports involving posttranscriptional miRNA silencing and asthma." (PMID 32512817, 2020). "The combined interaction scores resulted in higher interactions for the genes STAT3, AGO2, COL1A1, CLCN6, and KSR for moderate asthma and JAK2, INSR, ERBB2, NR3C1, and PTK6 for severe asthma." (PMID 32512817, 2020). "For example, in severe asthma, the combined interaction scores for the STAT3, AGO2, COL1A1, CLCN6, and KSR1 genes yielded a higher interaction for the moderate asthma phenotype, and the JAK2, INSR, ERBB2, NR3C1, and PTK6 genes were more interactive for the severe asthma phenotype." (PMID 32512817, 2020).